ZDHHC11 (zDHHC palmitoyltransferase 11)
Description:
Endoplasmic reticulum-localized palmitoyltransferase that could catalyze the addition of palmitate onto various protein substrates and be involved in a variety of cellular processes (By similarity). Has a palmitoyltransferase activity toward NCDN and regulates NCDN association with endosome membranes through this palmitoylation (By similarity). May play a role in cell proliferation. Also has a palmitoyltransferase activity-independent function in DNA virus-triggered and CGAS-mediated innate immune response. Functions as an adapter that recruits IRF3 to STING1 to promote the activation of that key transcriptional regulator of type I interferon (IFN)-dependent immune response.
Synonyms: ZNF399; FLJ13153
Tractability: Antibody: UniProt predicts a signal peptide or a membrane-spanning region. PROTAC: ubiquitination databases record sites on it.
Gene: Protein-coding gene on chromosome 5 (795,605 to 858,973, reverse strand). Ensembl gene ENSG00000188818.
Subcellular location: Endoplasmic reticulum membrane
Subcellular location (Human Protein Atlas): Golgi apparatus
Pathways (Reactome):
Disease: Maturation of spike protein
Gene Ontology:
Molecular function: protein binding; signaling adaptor activity; protein-cysteine S-palmitoyltransferase activity; palmitoyltransferase activity
Biological process: antiviral innate immune response; positive regulation of defense response to virus by host; peptidyl-L-cysteine S-palmitoylation; protein targeting to membrane
Cellular component: endoplasmic reticulum; endoplasmic reticulum membrane; endosome membrane; Golgi membrane
Genetic constraint (gnomAD): Loss-of-function variants: 39 observed, 35.01 expected, observed/expected ratio (o/e) 1.11, 90% interval 0.86 to 1.46. The upper end of that interval is the gene's LOEUF score, 1.46, which puts it in group 6 of 6, group 1 being the genes least tolerant of losing a copy. Missense variants: 383 observed, 378.81 expected, observed/expected ratio (o/e) 1.01, 90% interval 0.93 to 1.1. Synonymous variants: 146 observed, 146.5 expected, observed/expected ratio (o/e) 1, 90% interval 0.87 to 1.14.
Homologues: Orthologues: chimpanzee ZDHHC11 (92% identical), rat Zdhhc11 (43% identical), mouse Zdhhc11 (42% identical), zebrafish zdhhc11 (23% identical), Caenorhabditis elegans dhhc-2 (13% identical), Caenorhabditis elegans dhhc-9 (13% identical), Caenorhabditis elegans dhhc-12 (12% identical), Caenorhabditis elegans dhhc-4 (11% identical), Caenorhabditis elegans dhhc-5 (10% identical), Caenorhabditis elegans dhhc-7 (10% identical), Drosophila melanogaster CG1407 (10% identical), Drosophila melanogaster CG17287 (10% identical), and 1 more. Paralogues in human: ZDHHC11B (83% identical), ZDHHC1 (34% identical), ZDHHC14 (15% identical), ZDHHC4 (14% identical), ZDHHC3 (14% identical), ZDHHC18 (14% identical), ZDHHC19 (13% identical), ZDHHC7 (13% identical), ZDHHC9 (13% identical), ZDHHC23 (13% identical), ZDHHC12 (12% identical), ZDHHC6 (12% identical), and 5 more.
Diseases named in the same sentence as ZDHHC11 in open-access papers:
ZDHHC11 is named in the same sentence as 19 diseases in open-access papers, as found by Europe PMC text mining. Sharing a sentence is not in itself a finding about the gene and the disease. The quoted sentences say what the papers report.
Burkitt lymphoma (10 papers, 2021 to 2026). A rare form of malignant mature B-cell non-Hodgkin lymphoma. "Previous studies have indicated that ZDHHC11 and ZDHHC11B play critical roles in maintaining the oncogenic MYC-miR-150-MYB axis in Burkitt’s lymphoma, and ZDHHC11 may be a biomarker to identify high-risk bladder cancer patients with disease progression." (PMID 34490261, 2021). "Research in Burkitt lymphoma demonstrated a MYC-miR-150-ZDHHC11/B-MYB network, in which high levels of MYC repress miR-150, which leads to derepression of MYB, ZDHHC11 and ZDHHC11B, and promotes proliferation." (PMID 33593440, 2021). "We previously showed that ZDHHC11 promotes cell growth in Burkitt lymphoma (BL)." (PMID 41992423, 2026). "Moreover, ZDHHC11 mRNA expression was elevated in Burkitt lymphoma cells, and it could accelerate tumor proliferation." (PMID 35297315, 2022). "When a panel of BLBCL, Hodgkin and Burkitt lymphoma cell lines were compared to GCB cells it was revealed that MYC, ZDHHC11/B and MYB were upregulated and miR-150 was downregulated in all lymphoma types as compared to GCB." (PMID 34502399, 2021). "In Burkitt lymphoma, which is characterized by high MYC expression, two circRNAs, ZDHHC11 and ZDNN11B, containing multiple binding sites for miR-150 were upregulated following upregulation of the MYC that targets MYB." (PMID 34502399, 2021). "We previously showed that MYC promoted Burkitt lymphoma (BL) growth by inhibiting the tumor suppressor miR-150, resulting in release of miR-150 targets MYB and ZDHHC11." (PMID 38627588, 2024).
bladder cancer (4 papers, 2019 to 2023). "For example, overexpression of ZDHHC11 is strongly linked to high grade, disease progression, and unfavorable prognosis in bladder cancer, while patients with high ZDHHC11 expression exhibit favorable prognostic features in glioma." (PMID 37161425, 2023). "Cancer and DHHC enzymes are closely associated; for example, copy number variation of a chromosome region including the gene of ZDHHC11 is observed in lung and bladder cancers, and decreased expression of ZDHHC2 has been found in colorectal cancers and gastric adenocarcinoma." (PMID 30658672, 2019).
viral infection (3 papers, 2021 to 2025). "Functional analysis revealed that the overexpression of ZDHHC11 inhibited ZIKV infection, while ZDHHC11 knockdown enhanced viral infection." (PMID 36680184, 2023). "Notably, the study revealed that the overexpression of ZDHHC11 suppressed ZIKV infection, while ZDHHC11 knockdown enhanced viral infection." (PMID 36680184, 2023). "Next, we examined whether ZDHHC11 was involved in NF-κB activation induced by virus infection." (PMID 34490261, 2021). "The role of ZDHHC11 in ZIKV infection was investigated, and the results demonstrated that the overexpression of ZDHHC11 suppressed ZIKV infection in an enzymatic activity-dependent manner, while ZDHHC11 knockdown enhanced viral infections." (PMID 36680184, 2023).
colorectal cancer (2 papers, 2019 to 2022). A primary or metastatic malignant neoplasm that affects the colon or rectum. "hnRNP G‐T promoted cancer cell growth and mediated the stabilization of ZDHHC11 mRNA in colorectal cancer cells." (PMID 35384384, 2022).
ZIKV infection (2 papers, 2023 to 2024). "A study confirmed that a palmitoylation inhibitor 2-bromopalmitate enhanced ZIKV infection, which subsequently led to the identification of ZDHHC11 as a key enzyme of E protein palmitoylation." (PMID 39273370, 2024). "Overexpression and knock-out studies revealed that overexpression of ZDHHC11 inhibited ZIKV infection in HEK293T cells, whereas knock-out enhanced the ZIKV infectivity." (PMID 39273370, 2024). "Overall, these results suggested that the overexpression of ZDHHC11 inhibits ZIKV infection in an enzymatic activity-dependent manner." (PMID 36680184, 2023). "The viral titer in the supernatant of ZIKV-infected U251 cells was also determined and quantified using plaque assays, and the results demonstrated that ZIKV infection was dramatically attenuated following the overexpression of ZDHHC11." (PMID 36680184, 2023). "In conclusion, we proposed that the envelope protein of ZIKV undergoes a novel post-translational modification and identified a distinct mechanism in which ZDHHC11 suppresses ZIKV infections via palmitoylation of the ZIKV envelope protein." (PMID 36680184, 2023). "We also generated an inactivated form of ZDHHC11 (ZDHHS11) by inducing a mutation in the DHHC motif, and evaluated its effect on ZIKV infection." (PMID 36680184, 2023). "Notably, ZDHHC11 suppressed ZIKV infections in an enzymatic activity-dependent manner and ZDHHC11 knockdown promoted ZIKV infection." (PMID 36680184, 2023). "Consistent with this, the overexpression of ZDHHC11 also inhibited ZIKV infection in A549 cells." (PMID 36680184, 2023). "The results demonstrated that ZIKV infection increased significantly following ZDHHC11 knockdown." (PMID 36680184, 2023). "In this study, we also investigated the role of ZDHHC11 in ZIKV infections." (PMID 36680184, 2023). "Considering that ZDHHC11 is a multifunctional protein, it may be possible that it limits ZIKV infection by other cellular processes besides palmitoylating envelope proteins." (PMID 36680184, 2023).
B-cell lymphoma (1 paper, 2022). "As a next step, we tested the expression levels of the three individual ZDHHC11 transcripts in a set of 30 B-cell lymphoma cell lines and GC B-cells." (PMID 35205272, 2022). "The lymphoma specific role of ZDHHC11 remains to be elucidated and studying the individual ZDHHC11 products might provide further mechanistic insights in different B-cell lymphoma subtypes." (PMID 35205272, 2022).
diffuse large B-cell lymphoma (1 paper, 2022). "Here we studied the relevance of the MYC/miR-150/MYB/ZDHHC11 network in two other GC B-cell derived lymphomas, i.e., Hodgkin lymphoma (HL) and diffuse large B-cell lymphoma (DLBCL)." (PMID 35205272, 2022).
hepatoblastoma (1 paper, 2023). Hepatoblastoma (HB) is a malignant hepatic tumor and is the most common pediatric liver cancer. "The CNV of ZDHHC11 and ZDHHC11B are associated with hepatoblastoma and primary open-angle glaucoma." (PMID 37403156, 2023).
lymphoma (1 paper, 2022). A malignant (clonal) proliferation of B- lymphocytes or T- lymphocytes which involves the lymph nodes, bone marrow and/or extranodal sites. "In conclusion, although MYC, MYB and ZDHHC11 all have important roles in the growth of HL and DLBCL, the network, as defined in BL with a critical role of miR-150, is not broadly applicable to other GC B-cell derived lymphoma subtypes." (PMID 35205272, 2022).
melanoma (1 paper, 2025). A malignant, usually aggressive tumor composed of atypical, neoplastic melanocytes. "In our study, ZDHHC11 was an unfavorable factor in melanoma and related to immune cells." (PMID 40909968, 2025). "In GSE46517, IFFO1, ANKRD10, CLPB, TCAP, and POLG2 displayed high expression, but the expression levels of CHMP4A, ZDHHC11, and ANKMY1 were low in the melanoma group." (PMID 40909968, 2025). "ZDHHC11 and CLPB exhibited inconsistent expression trends between TCGA data and melanoma cells." (PMID 40909968, 2025).
cancer (6 papers, 2019 to 2025). A tumor composed of atypical neoplastic, often pleomorphic cells that invade other tissues. "Previous studies have shown that ZDHHC11 is an ER-associated protein and that its aberrant expression is related to the development of some cancers." (PMID 34490261, 2021). "Although the gene carried various types of mutations within the same sample, we suspected the passenger nature of these mutations in ZDHHC11 partly due to scarce reports on mutated ZDHHC11 in cancer and the potentially benign consequence of these mutations." (PMID 34285259, 2021). "An IP‐transcriptome analysis revealed that hnRNP G‐T bound with and regulated numerous mRNAs, including apoptosis‐related mRNAs, as well as ZDHHC11 mRNA, suggesting that the cancer progression pathway, which mainly regulates apoptosis, is regulated by hnRNP G‐T in CRC cells." (PMID 35384384, 2022). "We herein report that hnRNP G‐T promoted cancer cell growth and stabilized mRNA of ZDHHC11 in CRC." (PMID 35384384, 2022). "Because NF-κB signaling plays a crucial role in cancer initiation and progression, whether the function of ZDHHC11 in cancer development is related to its regulatory role in NF-κB signaling needs to be investigated further." (PMID 34490261, 2021). "Several top-ranking genes, such as MEIS1, ZDHHC11, CWH43, TTC12, and CDH22, have been supported by recent studies as playing roles in various cancers and aging-related processes." (PMID 39499149, 2024).
tumor (3 papers, 2022 to 2024). "To investigate the tumor‐promotive mechanism of ZDHHC11 in CRC cells, we performed a transcriptome analysis in ZDHHC11‐downregulated HCT116 cells." (PMID 35384384, 2022). "In conclusion, we revealed that hnRNP G‐T was abnormally expressed in CRC and that it promoted tumor growth in CRC through ZDHHC11‐mediated inhibition of apoptosis." (PMID 35384384, 2022). "Our western blotting experiment showed that ERK signaling as well as ATM/ATR signaling was attenuated by the downregulation of hnRNP G‐T and ZDHHC11, supporting that the hnRNP G‐T‐ZDHHC11 pathway promoted tumor progression, which mediated the ATM/ATR signaling pathway." (PMID 35384384, 2022). "Likewise, hnRNP G‐T supported cell growth and inhibited apoptosis by the direct stabilization of the tumor promotive ZDHHC11 mRNA, and thereby promoted the progression of CRC." (PMID 35384384, 2022). "However, the association of ZDHHC11 with CRC and the mechanism underlying its tumor proliferative functions have not been reported." (PMID 35384384, 2022).
ZDHHC11 also shares sentences with these, for which no sentence is quoted: cervical cancer (1 paper); gastric adenocarcinoma (1); glioma (1); Hodgkins lymphoma (1); infection (1); non-small cell lung carcinoma (1); primary open-angle glaucoma (1).